CASP1 (caspase 1)
Diseases named in the same sentence as CASP1 in open-access papers (continued):
Sharing a sentence is not in itself a finding about the gene and the disease.
infection (continued). "Inflammasomes are inducible multi-protein platforms in phagocytic cells that are required for activation of caspase 1 by induced proximity during the inflammatory host response following pathogen infection and tissue damage." (PMID 20482797, 2010). "We measured the activation of caspase-1 after infection of macrophages with M. leprae because the maturation and secretion of IL-1β is dependent on the activation of caspase-1." (PMID 20671924, 2010). "Such analysis demonstrated a 2.6-fold increase of mature IL-1β in the tails of mice infected with wild type M. marinum compared to ΔRD1 infection, suggesting that Esx-1 promotes caspase-1 activation in vivo." (PMID 20463815, 2010). "With knockout mice deficient in caspase-1 and several inflammasome components and a growing number of useful infection models at hand, investigating the involvement of WxxxE GEFs in caspase-1 activation will be an interesting task for future research." (PMID 20195519, 2010). "We also show that Naip5 contributes to caspase-7 activation downstream of caspase-1 during physiological levels of infection." (PMID 19343209, 2009). "We propose that wild-type Naip5 mediates the activation of caspase-7 by caspase-1 during infections at low MOI." (PMID 19343209, 2009). "While caspase-1 activation protects the host from various pathogens during infection, excessive caspase-1 activation contributes to various inflammatory disorders and septic shock." (PMID 19924255, 2009). "Our data show that at physiological stages of infection, L. pneumophila leads to caspase-7 activation in a caspase-1–dependent manner." (PMID 19343209, 2009). "Accordingly, mouse macrophages that do not activate caspase-1 in response to L. pneumophila such as Nlrc4−/− and caspase-1−/− cells are permissive to infection." (PMID 19343209, 2009). "Using the intracellular pathogen L. pneumophila, we show that, upon infection of murine macrophages, caspase-7 was activated downstream of the Nlrc4 inflammasome and required caspase-1 activation." (PMID 19343209, 2009). "N. caninum infection induces the release of IL-1β and IL-18, cleaved caspase-1, and cell death in mouse bone marrow-derived macrophages, while infection of mice deficient in NLRP3, ASC, and caspase-1/11 leads to a decrease in IL-18 production and an increase in IFN-γ in the serum." (PMID 41357231, 2025). "However, at this stage, we cannot rule out a potential role of direct cell contact or short-lived metabolites in bystander cell caspase-1 activation during infection." (PMID 40053580, 2025). "Similarly, IBV Conn A5968 infection significantly enhanced caspase-1 activity in chicken macrophages at 24 hpi (p < 0.0001)." (PMID 40284946, 2025). "In this study, we show that caspase-1 is required to restrict intracellular Salmonella replication early during infection in human macrophages, and that caspase-4 enables the restriction of Salmonella later during infection." (PMID 40162563, 2025). "However, the mRNA levels of NLRP3 and caspase-1 were decreased in the Pro10, Pro20, Pro40, Amo20, Pro20 + Amo20, and Bai100 groups compared with the infection group (p < 0.01)." (PMID 40305201, 2025). "Importantly, adoptive transfer of only caspase-1+/+ alveolar macrophages before secondary infection of post-CLP mice was able to restore the control of bacterial burden in the lungs to the level of healthy mice." (PMID 40202049, 2025). "Interestingly, we have previously reported that IAV infection of human bronchial epithelial cells also results in cleavage of GSDMD, as well as the effector caspase-1 at 24 h post-infection." (PMID 40481027, 2025). "Likewise, pro-IL-1β expression and caspase 1 were also enhanced in S. Typhimurium-infected sip62 BMDMs compared to siCtrl BMDMs at 6h post infection when autophagy is inhibited and p62 accumulates." (PMID 40276384, 2025).
infection (continued). "We have previously shown that the vDUB encoded in the N terminus (aa 1–235) of the EBV large tegument protein BPLF1 is released by CASP1 (caspase 1) cleavage during productive infection and the active enzyme localizes in the nucleus and cytoplasm of the infected cells." (PMID 39842454, 2025). "Whereas caspase-1 is the primary caspase that mediates inflammasome responses and control of Salmonella burdens in human macrophages, our data indicate that caspase-4 also plays a role at a later stage of infection." (PMID 40162563, 2025). "However, this is dependent on caspase 1 as infection of caspase 1/11 and caspase 1 knockout macrophages with a ΔPknF strain results in no IL-1β production." (PMID 40261010, 2025). "We found that the caspase-1- and caspase-4-deficient cells exhibited significantly increased proliferation compared to Cas9 cells during unstimulated conditions and during HK1655 infection." (PMID 40137780, 2025). "Moreover, pneumococcal infection-induced ROS suppressed the activation of caspase-1 within 4 h after infection." (PMID 37697221, 2024). "Besides TLRs, S. mansoni infection also induced higher levels of inflammasome involved-molecules as NLRP1, NLRP3 and Caspase-1 in the second week of infection." (PMID 38896633, 2024). "Furthermore, P1/7 induced NLRP3 inflammasome activation with increased protein expression of NLRP3 and caspase-1 at 9 h post-infection (hpi), leading to the production of inflammatory cytokines, including IL-1β and IL-6." (PMID 39334337, 2024). "To confirm that infection with A. actinomycetemcomitans triggers the release of IL-1β from macrophages, we checked the activation of inflammasomes in macrophages, which regulate IL-1β maturation following caspase-1 activation in response to infection with A. actinomycetemcomitans." (PMID 39143049, 2024). "Interestingly, immunized Casp1/4−/− mice fared better than immunized wildtype mice against bacterial dissemination as demonstrated by spleen burdens 24 h post-infection." (PMID 38594380, 2024). "The number and frequency of CD45+ cells were slightly increased with a neutrophil number detected at the site of infection that was significantly more elevated in Casp1-/- mice compared to control mice, while that of monocytes, and dendritic cells was not significantly increased." (PMID 39250503, 2024). "Rather, pyroptic cell death by CASP1 mediates infection clearance." (PMID 39392284, 2024). "Therefore, we infected Casp1 single knockout mice with 10 cysts of Me49 type II strain parasite by intraperitoneal (i.p) infection." (PMID 39446964, 2024). "Taken together, these results indicate that caspase-1 and −11 are involved in the infection-induced upregulation of IL-22 in the gut, consequently inducing the expression of antimicrobial C-type lectins as well as Fut2, which encodes for an enzyme important for fucosylation in the gut." (PMID 39428744, 2024). "The thickening of the b1 and b2 layers upon S. Typhimurium infection was significantly less in the Casp1/11−/− mice as compared to WT mice suggesting that inflammasome signaling impacts mucin release both close to the site of infection (proximal colon), as well as in the distal colon." (PMID 39428744, 2024). "Additionally, during chronic infection at six weeks post-infection (6 wpi), we found a 1.4-fold increase in parasite burden in the brains of Casp1 KO mice relative to control mice." (PMID 39446964, 2024). "Conversely, caspase-1 can also work to protect pulmonary barrier function during infection." (PMID 38410714, 2024). "Inflammatory caspases (caspase-1, caspase-4, and caspase-5 in humans, and caspase-11 in mice) play key roles in the innate immune response against pathogen infection and regulate the production of the pro-inflammatory cytokines: interleukin 1 beta (IL-1β) and IL-18, leading to pyroptosis." (PMID 39625520, 2024).
infection (continued). "One arm of the caspase-1 response mediates IL-18 release to impact T cell cytokine production and pathogen control, while other arms stimulate signaling (including through IL-1RAP), to mediate cellular recruitment to the site of infection." (PMID 39446964, 2024). "This may be due to the increased expression of NLRP3, apoptosis-associated speck-like protein (ASC), caspase-1, and GSDMD associated with pyroptosis in the host upon infection." (PMID 39011036, 2024). "In the brains of BALB/c mice we could also observe an activation of caspase-1 after infection with the wild-type 93/4286, while a much lower activation was observed in the brains of mice infected with the 93/4286ΩhrpB mutant." (PMID 39376663, 2024). "The underlying mechanism may involve inflammasome activation, and triggers immune cell pyroptosis defense against pathogen infection via caspase-1/GSDMD pathway." (PMID 39011036, 2024). "In addition, the increased percentage of the sub-G1 population and level of LDH release following hvKp infection in WT BMDMs were inhibited in Caspase-1-/- BMDMs." (PMID 37457695, 2023). "Since caspase-1 drives the inflammation-mediated pyroptosis mechanism for non-programmed cell death, a higher level of active caspase-1 in the EVs after CCoV infection indicates inflammation and severe infection." (PMID 36979955, 2023). "Abortive infection leads to impaired reverse transcription, hence presence of reverse transcripts, death of abortively infected cells by pyroptosis, and release of inflammasome byproducts such as caspase-1." (PMID 37953818, 2023). "Therefore, we examined the effects of a caspase-1 inhibitor (Ac-YVAD-cmk) on the production of LDH upon infection." (PMID 37457695, 2023). "Infection with YT strain leads to liver injury and could activate inflammation associated with the TLR–JNK–NF-κB pathway and caspase-1 inflammasomes." (PMID 37063902, 2023). "Considering that STEC infections usually occur at low infective doses, it is dared to speculate that at the beginning of the infection, neutrophils recruited to the gut secrete high IL-1β levels through a mechanism that involves caspase-1 and NSPs activity." (PMID 38127952, 2023). "Next, we performed H. pylori SS1 infection studies in WT, Nlrp3−/−, Pycard−/−, and Casp1−/− mice." (PMID 37365163, 2023). "However, one set of type II ISGs was also upregulated in male-derived neutrophils following infection e.g. Casp1, CtsI, Ccl2." (PMID 38179044, 2023). "In addition, pretreatment of BMDMs with MitoQ also significantly inhibited cell death, Caspase-1 activation, and IL-1β secretion in case of ΔfliCΔsiiD or ΔfliCΔsiiD::Vector infection." (PMID 37155697, 2023). "These variants were found in inflammasome genes (NLRP1/3 and CASP1), genes mediating inflammasome inactivation via auto- and mitophagy (RIPK2 and MEFV), and genes involved in the response to infection with DNA viruses (POLR3A, DHX58, and IFIH1) and type-1 interferons (TYK2 and PTPRC)." (PMID 37626706, 2023). "Moreover, when measuring biomarkers of inflammation after recovery from active infection, caspase-1 and ASC presented AUC values above 0.9." (PMID 37168848, 2023). "Pyroptosis, a extremely inflammatory and Caspase-1-dependent form of programmed cell death, is a common reaction to intracellular pathogen infection and is a component of the immune system’s fight against infection." (PMID 37767093, 2023). "We anticipate that elevated levels of caspase-1 could be due to ongoing low levels of abortive infection among those ART-treated individuals with persistent immune activation despite peripheral HIV viral suppression." (PMID 37953818, 2023). "Our data show that recognition of T3SS-expressing P. aeruginosa strains by the caspase-1 dependent canonical inflammasome leads to pro-inflammatory responses, manifested by increases in caspase-1-activation, IL-1β, and IL-18 cytokine production, and leukocyte migration to the site of infection." (PMID 35277504, 2022).
infection (continued). "The data demonstrated that Casp-1 is involved in the activation of IL-1β during SVA infection." (PMID 35254168, 2022). "In addition, AIM2 knockout mice are more susceptible to Brucella infection and infection of C57BL/6, NLRC4, NLRP3, AIM2, ASC and Caspase-1 KO (knockout) BMDM (bone marrow-derived macrophage) with B. abortus than wild-type control mice." (PMID 36068262, 2022). "Inability to discern the role of Casp-1,11 in B6 mice in vivo may be related to the rapid fatality of wild-type mice within the first week of infection." (PMID 34864057, 2022). "Cleaved caspase-1 was observed in the supernatant upon infection with the mutant." (PMID 36128739, 2022). "Unsurprisingly, infection with all of the strains resulted in Caspase-1 cleavage." (PMID 36318583, 2022). "Therefore, in summary, stimulation of THP-1 with P. acnes leads to the expression of active caspase-1(p10) and IL-1β in an infection-dependent manner." (PMID 35871079, 2022). "In this study, SFTSV infection induced processing of pro-caspase-1 and subsequent maturation and secretion of IL-1β/IL-18 were significantly suppressed in human PBMCs when NLRP3 gene was knocked down by specific shRNA or inhibited by a specific inhibitor, glibenclamide." (PMID 35173184, 2022). "We have preliminary data at this stage to indicate that platelets may also secrete IL-1β with pro-caspase-1 processed upon infection with SFTSV." (PMID 35173184, 2022). "Inflammasome activation with cleavage of caspase-1 and secretion of IL-1β is not affected in the absence of caspase-7, as well as induction of cell death and in vivo susceptibility to infection." (PMID 36532444, 2022). "Subsequent studies have shown that cells deficient in caspase-1/-11 or caspase-8/RIPK3 still undergo cell death in response to the infection, while cells deficient in caspase-1/-11/-8/RIPK3 or cells deficient in caspase-1/-11/-12/-8/RIPK3 are protected from cell death." (PMID 35563804, 2022). "Our data showed that ECHO 11 infection or LPS/Nigericin treatment induced pro-IL-1β maturation, and CASP-1/GSDMD cleavages in THP-1 cells, and these activations were remarkably attenuated by knocking down either one of the NLRP3 inflammasome components and pyroptosis." (PMID 36026486, 2022). "Caspase-1 is activated by different inflammasomes during various infections and immune responses." (PMID 35991122, 2022). "A previous study has shown that during the interaction between BMDMs and C. albicans, the stimulus of ~1–3 h post infection represents the early phagocytosis events, and the ~6 h of treatment terms the initial fungal escape following caspase-1-dependent pyroptosis." (PMID 35729111, 2022). "Nevertheless, caspase-11 is reported to be different from caspase-1 in the defense of infection." (PMID 35982051, 2022). "Similarly, co-deletion of ASC or caspase-8/RIPK3 with caspase-1/-11 phenocopies NLRC4 deletion during challenge with flagellin or infection with Legionella." (PMID 35563804, 2022). "Additionally, infection of J774A.1 mouse macrophage with Mbov results in activation of caspase-1 as early as 6h post-infection." (PMID 35237260, 2022). "LPS along with Nigericin or SVA infection could induce IL-1β secretion and IL-1β maturation, but VX-765 (Casp-1 inhibitor) inhibited SVA-induced IL-1β production." (PMID 35254168, 2022). "Interestingly, in caspase-1-knockdown cells IL-18 was increased upon CFT073 infection, but the expression of the IL-18 receptor was reduced to basal levels." (PMID 35132157, 2022). "While pyroptosis protects the host against infections, inappropriate or excessive caspase-1 activity and pyroptosis may be detrimental." (PMID 36189207, 2022). "NLRP3 activation and caspase-1-dependent pyroptosis occurs also after infection with the HCV." (PMID 34201847, 2021). "Additionally, caspase-1 activity assay revealed that ΔpknF mutant results in increased activation of caspase-1 in BMDMs, in contrast to infection with Mtb and complement ΔpknF::pknF." (PMID 34324582, 2021).
infection (continued). "Therefore, it is not surprising that pathogens have evolved mechanisms to limit the activation of caspase-1 in response to infection." (PMID 34201847, 2021). "The keywords of red cluster are cell death, inflammasome, caspase-1 and infection." (PMID 34484243, 2021). "However, IL-1β and cleaved caspase-1 secretion stimulated by SFTSV infection or LPS/Nigericin were all inhibited by the inhibitor CY-09." (PMID 33708197, 2021). "The analysis of variance between IL-1β, IL-18, IL-6, IL-8 and caspase-1 levels, showed statistically significant differences related to the infection conditions or the time after infection (6, 18 and 24 h.p.i.)as well as the interaction between these two factors." (PMID 34947890, 2021). "Infection with T. cruzi results in the activation of caspase-1 and inflammasome formation." (PMID 34832980, 2021). "Bt infected ASC and CASP1 KO cells produced significantly lower amounts of IL-1β as compared to wildtype cells, confirming that pyroptosis and its downstream signalling pathways were activated during Bt infection." (PMID 34821529, 2021). "Moreover, cell death compared to wild-type BMDMs was significantly reduced in both Casp1-/- and Casp11-/- BMDMs during infection with ΔpknF mutant." (PMID 34324582, 2021). "At 6 and 12 h post-infection, the mRNA expression levels of caspase-3, caspase-1, GSDMD, RIPK3, MLKL, NLRP3, IL-1β, and IL-18 were upregulated in RAW264.7 macrophages infected with either E. faecalis CA1, CA2, or OG1RF strains compared to the levels in the control group." (PMID 34513732, 2021). "Similarly, infection with herpes simplex virus 1 (HSV-1), a DNA virus of the Herpesviridae family, caused strong caspase-1 activation and pro-IL-1β maturation." (PMID 34201847, 2021). "Vaccinia virus (VACV) infection induces NLRP3-independent maturation of caspase-1." (PMID 34638790, 2021). "However, in the presence of a low degree of infection, inhibition of autophagy is released, resulting in cell protection; when autophagy cannot eliminate intracellular infection, caspase-1 is activated to initiate pyroptosis." (PMID 34759265, 2021). "Likewise, the host should possess means to neutralise pathogen-mediated regulation of caspase-1 activity and successfully control the infection." (PMID 35008798, 2021). "In contrast, after pretreatment with IFN-γ to mimic the inflammatory environment that develops during an in vivo infection, high pathogen loads only developed in Casp1/11−/− monolayers, indicating that both caspase-1 and caspase-11 exert potent antimicrobial responses within “inflamed” IECs." (PMID 32282854, 2020). "Thus, TLR2 activation by RSV and ROS generation during infection will promote formation of ASC-NLRP3 inflammasome complex that activates caspase-1 for Gasdermin-D mediated pyroptosis." (PMID 32854254, 2020). "However, infection-induced small amounts of IL-1β secretion gradually increased at a later time point, which again suggests an inflammasome/caspase-1 independent mechanism for this in human THP-1 cells." (PMID 32230726, 2020). "To further evaluate whether Caspase-1/11 and Gsdmd were involved in the IL-1β release in response to the SS2 infection in vivo, we also injected IP WT, Caspase-1/11−/−, and Gsdmd−/− mice with lower dose of 2 × 108 CFU SS2." (PMID 32922370, 2020). "Treatment of caspase-1 KO mice with IL-1β microparticles significantly reduced S. aureus burden in the brain and galea compared to empty microparticles, confirming the critical role of IL-1β in limiting S. aureus outgrowth during craniotomy infection." (PMID 32290861, 2020). "Furthermore, we pretreated BMDMs with the Nlrp3 inhibitor (MCC950) and Caspase-1 inhibitor (Z-YVAD-FMK) prior to the infection with SS2, and we observed the expected significant inhibitions to the IL-1β release and cytotoxicity." (PMID 32922370, 2020).